Y_RNA (Y RNA )
Gene: Miscellaneous RNA gene on chromosome 4 (125,362,819 to 125,362,929, forward strand). Ensembl gene ENSG00000201297.
Homologues: Orthologues: chimpanzee Y_RNA (99% identical), macaque Y_RNA (94% identical), zebrafish Y_RNA (59% identical). Paralogues in human: Y_RNA (80% identical), Y_RNA (79% identical), RNY1 (78% identical), Y_RNA (78% identical), Y_RNA (77% identical), RNY1P5 (76% identical), Y_RNA (76% identical), RNY1P11 (75% identical), Y_RNA (75% identical), Y_RNA (74% identical), RNY1P1 (73% identical), RNY1P8 (73% identical), and 90 more.